INS (insulin)
Diseases named in the same sentence as INS in open-access papers (continued):
Sharing a sentence is not in itself a finding about the gene and the disease.
rubella (1 paper, 2019). A viral infection caused by the rubella virus. "Futhermore in case of rubella and other viruses such as coxsackieviruses, neonatal T cells react with viral peptides and cross-react with an antigen in the insulin-producing pancreatic beta islet cells resulting in an autoimmune destruction of the islet cells." (PMID 30829107, 2019).
sarcoidosis (1 paper, 2024). Sarcoidosis is a multisystemic disorder of unknown cause characterized by the formation of immune granulomas in involved organs. "We also carried out secondary analyses for T1D and sarcoidosis restricted to the insulin and non‐immune pathways, respectively." (PMID 39506244, 2024).
scleredema (1 paper, 2025). "One study reported a worsening of scleredema during insulin glargine administration, which improved after switching to regular insulin." (PMID 41149080, 2025).
scleritis (1 paper, 2023). Inflammation of the sclera. "Therefore, establishing a link between insulin and scleritis is prospective, and further studies are needed to determine the effectiveness of insulin in treating scleritis." (PMID 37063831, 2023). "Although no information has been reported on insulin for the treatment of scleritis, the role of insulin in treating inflammation cannot be underestimated." (PMID 37063831, 2023).
sexually transmitted infections (1 paper, 2024). "A significant statistical association was only observed for sexually transmitted infections at sampling (p = 0.023) and insulin (p = 0.002)." (PMID 38673551, 2024).
silicosis (1 paper, 2022). Silicosis is a respiratory disease caused by breathing in (inhaling) silica dust. "To determine whether a similar mechanism might be induced by silicosis-induced hippocampal inflammation, we examined pSer473-Akt levels as a proxy of activity of the insulin signaling pathway." (PMID 36527099, 2022).
skin aging (1 paper, 2023). The gradual irreversible changes in structure of skin that occur as a result of the passage of time.. "Results showed that 39 circadian rhythm-related genes (CRGs) were identified in skin aging, and these CRGs were enriched in signaling pathways such as glucagon signaling pathway, insulin resistance, thyroid hormone signaling pathway, and adipocytokine signaling pathway." (PMID 37905958, 2023).
sleep-wake disorder (1 paper, 2023). Abnormal sleep-wake schedule or pattern associated with the circadian rhythm which affect the length, timing, and/or rigidity of the sleep-wake cycle relative to the day-night cycle. "Circadian rhythm disturbances has been reported to be associated with elevated levels of both blood glucose and insulin, and this mechanism may explain the association between IPFD and circadian rhythm sleep-wake disorders." (PMID 37576958, 2023).
small intestinal tumors (1 paper, 2015). "However, feed intake, number and size (data not shown) of small intestinal tumors, GTT results, nonfasted blood glucose levels (data not shown), insulin and TNFα levels were not significantly different between the ob/wt and wt/wt mice." (PMID 26347815, 2015).
SOFT syndrome (1 paper, 2024). "We thus recommend to perform fasting insulin/glucose measurements, and OGTT in case of normal fasting measurements in all patients with SOFT syndrome as soon as they are diagnosed, even before puberty." (PMID 39017987, 2024).
Sotos syndrome (1 paper, 2023). Sotos syndrome is a rare multisystemic genetic disorder characterized by a typical facial appearance, overgrowth of the body in early life with macrocephaly, and mild to severe intellectual disability. "The precise mechanism of dysregulated insulin secretion in Sotos syndrome is unknown." (PMID 37065762, 2023).
sponge kidney (1 paper, 2013). "This case adds to the scarce body of literature of associated renal manifestations with RMS, including medullary sponge kidney, across the spectrum of insulin resistance." (PMID 23497647, 2013).
streptococcal infection (1 paper, 2010). Any of the several infectious disorders caused by members of streptococcus, a genus of gram positive bacteria belonging to the family Streptococcaceae. "Based on the relationship between PDI expression and insulin degradation, we tested the hypothesis that streptococcal infections and the resulting anti-PDI autoantibodies could have deleterious effects on insulin metabolism." (PMID 20886095, 2010).
Strongyloides infection (1 paper, 2023). "In a second study, individuals with T2DM and Strongyloides infection had similar hemoglobin A1c and random blood glucose levels, but lower insulin and glucagon levels, compared to uninfected individuals with T2DM at baseline." (PMID 36827239, 2023).
subacute thyroiditis (1 paper, 2023). Self-limited inflammation of the thyroid gland characterized by the presence of multinucleated giant cells. "Intrathyroidal injection using an insulin pen filled with a mixture of lidocaine and triamcinolone acetonide is a therapy for subacute thyroiditis (SAT) reported by us previously." (PMID 36468926, 2023).
systemic mycosis (1 paper, 2018). A mycosis that involves the lungs, abdominal viscera, bones and or central nervous system. "We evaluated the role of insulin in inflammatory parameters in diabetic and nondiabetic mice using a systemic mycosis Paracoccidioides brasiliensis (Pb) model." (PMID 30426021, 2018).
Talipes equinovarus (1 paper, 2020). Talipes equinovarus (also called clubfoot) typically has four main components: inversion and adduction of the forefoot; inversion of the heel and hindfoot; equinus (limitation of extension) of the ankle and subtalar joint; and internal rotation of the leg. "In our study, congenital anomaly was seen only in one case of the insulin treated group in form of congenital talipes equinovarus." (PMID 33403188, 2020).
thyroid hormone resistance (1 paper, 2024). "Individuals with thyroid hormone resistance may exhibit elevated levels of circulating cholesterol and triglycerides, decreased levels of HDL‐C, and decreased systemic insulin sensitivity." (PMID 38680023, 2024).
treatment-resistant hypertension (1 paper, 2017). "Our results indicate that RDN may improve insulin sensitivity in some patients with treatment-resistant hypertension, albeit confirmation of these indications of beneficial effects on leaner subjects awaits the outcome of larger randomized controlled studies." (PMID 29082259, 2017).
Vertigo (1 paper, 2007). An abnormal sensation of spinning while the body is actually stationary. "The inner ear is particularly sensitive to altered blood glucose and insulin levels; the most common symptoms are vertigo, hearing loss, tinnitus and ear fullness, among others." (PMID 17684656, 2007).
vestibular disorder (1 paper, 2009). Pathological processes of the vestibular labyrinth which contains part of the balancing apparatus. "Charles and Kirtane12, 13 found more alterations in the insulin index in patients with vestibular disorders when compared to normal volunteers, with a statistically significant difference." (PMID 19893939, 2009). "Nonetheless, there is no consensus whether the glucose-insulin index could have a diagnostic advantage over the glycemic index alone and fasting glucose in patients with vestibular disorders." (PMID 19893939, 2009).
Vitamin B3 deficiency (1 paper, 2022). Vitamin B3 deficiency is a condition that occurs due to not enough niacin (vitamin B3). "Expression of seven genes that previously were shown to respond to mild vitamin B3 deficiency in male white adipose tissue were not differentially expressed between the female dietary groups, neither was insulin sensitivity." (PMID 34338868, 2022). "Mild vitamin B3 deficiency, not inducing Pellagra, was, for example, shown to affect insulin sensitivity." (PMID 34338868, 2022).
Von Hippel-Lindau syndrome (1 paper, 2025). "However, following systematic treatment, patients with VHL syndrome were able to control rapidly and effectively their blood glucose using insulin therapy." (PMID 40989257, 2025).
Weaver syndrome (1 paper, 2022). Weaver syndrome (WVS) is a rare, multisystem disorder characterized by tall stature, a typical facial appearance (hypertelorism, retrognathia) and variable intellectual disability. "Upstream of IGF2 overlapping INS and INS-IGF2 the pattern of hypomethylation in Sotos and Weaver syndrome was consistent." (PMID 36064314, 2022). "The DMR called for Weaver syndrome overlaps the IGF2 gene and is composed of sites with a small effect size (Δβ ~ 0.05), with hypermethylation over a region of the IGF2 gene body and hypomethylation further upstream overlapping the INS and INS-IGF2 genes." (PMID 36064314, 2022).
withdrawal syndrome (1 paper, 2011). "After western authors published their work proposing insulin and grape-sugar for the management of withdrawal syndrome, Strelchuk and other psychiatrists introduced the use of insulin to Soviet narcological practice as well." (PMID 22208726, 2011).
Xanthelasma (1 paper, 2015). The presence of xanthomata in the skin of the eyelid. "Using Univariate logistic regression model, significant risk factors associated with the development of NAFLD were; double chin, buffalo hump, skin tag, xanthelasma, systolic blood pressure, WC, BMI, %BF, TG, fasting insulin, HOMA-IR and Hs-CRP." (PMID 26599361, 2015).
metabolic disorders (3,602 papers, 2006 to 2026). "Given that DA dysfunction is implicated in both depression and metabolic disorders, further examining the interaction between insulin signaling and DA pathways is critical for understanding how metabolic disturbances contribute to NPS." (PMID 40819304, 2026). "Increased senescence in SkM cells also leads to reduced insulin signaling and action, as in adipose and many other cell types implicated in metabolic diseases." (PMID 41189469, 2026). "Hyper-activated insulin signaling systems cause IR, the principal complication behind many metabolic disorders." (PMID 40628905, 2025). "The expression of the CLSTN2 gene is associated with glucose and insulin metabolism, contributing to their regulation and the onset of metabolic disorders." (PMID 40509051, 2025). "T2DM is defined as a metabolic disorder characterized by relative insulin deficiency due to impaired insulin secretion and insulin sensitivity, leading to chronic hyperglycemia." (PMID 41048293, 2025). "Oral UDCA promoted weight loss and mitigated a similar cluster of metabolic disease characteristics in lean, obese, and aged mice, including lowering blood glucose, lipids, hepatic triglycerides, cholesterol, insulin resistance, and proinflammatory cytokines." (PMID 39235984, 2025). "T2D is the most common metabolic disease and has become a global epidemic, and the hyperglycemia is a hallmark of T2D, caused by insufficient insulin secretion." (PMID 40332366, 2025). "Metabolic diseases are also linked with autophagy impairment, such as obesity, diabetes, and liver diseases, as autophagy coordinates lipid metabolism, insulin sensitivity, and mitochondrial functions." (PMID 40444035, 2025). "These genes are involved in the regulation of energy metabolism and insulin sensitivity, and their polymorphic variants have been associated with an increased susceptibility to metabolic disorders." (PMID 41300761, 2025). "It is a metabolic disorder characterized by high blood glucose levels resulting from various pathogenic processes, including insufficient insulin secretion, resistance to insulin action, or both." (PMID 41488069, 2025). "Elevated magnesium levels in the spleen appear to be inversely associated with certain markers of metabolic disorders, suggesting that magnesium’s anti-inflammatory and insulin-sensitizing properties extend to immune-related tissues." (PMID 41010443, 2025). "Omentin exhibits anti-inflammatory effects and sensitises tissues to insulin action, and its reduced levels are a risk factor for metabolic diseases." (PMID 40491594, 2025). "Metabolic disorders have traditionally been attributed to an absolute or relative deficiency of insulin, a perspective known as the insulin-centric theory." (PMID 41149695, 2025). "Glucose-sensing ChREBP and MondoA are transcriptional factors involved in the lipogenic, inflammatory, and insulin signaling pathways implicated in metabolic disorders; however, limited ocular studies have been conducted on these proteins." (PMID 39851533, 2025). "Prior studies have linked ribosomal protein dysregulation—especially RPL11—to metabolic disorders: RPL11 downregulation in pancreatic β-cells impairs insulin secretion, while ribosomal stress in endothelial cells exacerbates diabetic macroangiopathy." (PMID 41384025, 2025). "The OVX model is commonly used to study metabolic diseases associated with estrogen deficiency, and it shows fundamental changes in insulin sensitivity, glucose tolerance, and body weight." (PMID 41169786, 2025). "It has been implicated in insulin signaling regulation by targeting the insulin receptor, positioning it as a potential therapeutic target in metabolic diseases." (PMID 41035649, 2025). "It was observed that, in terms of insulin secretion coefficient, 61% of participants were at risk of developing a metabolic disorder, followed by 37% who were at risk of becoming obese." (PMID 40426847, 2025).
metabolic disorders (continued). "This will allow for developing novel dietary strategies for improving insulin sensitivity and reducing the risk of metabolic disorders by modulating carbohydrate metabolism in the gut, central to the whole-body glucose homeostasis." (PMID 40076251, 2025). "Enriched pathways included ErbB signaling, insulin signaling, and focal adhesion, which are implicated in neurodegeneration, fibrosis, and metabolic disorders." (PMID 40732226, 2025). "T2D is a metabolic disorder characterized by metabolic dysregulation of glucose due to loss of insulin sensitization and impaired insulin secretion from pancreatic β cells." (PMID 39458933, 2024). "HES1, for example, is involved in the regulation of developmental processes and cell differentiation, and its association with metabolic diseases suggests a potential role in the regulation of pancreatic β-cell function and insulin secretion." (PMID 39926598, 2024). "Considering the close association between PCOS and metabolic disorders, we evaluated insulin sensitivity within the various groups." (PMID 38665877, 2024). "In recent years, some studies have highlighted its association with metabolic disorders, such as alterations in insulin structure, the generation of reactive oxygen species, and the disorder of glucose and lipid metabolism." (PMID 39590952, 2024). "A reduction in insulin sensitivity can also cause increased lipid mobilization, leading to severe metabolic disorders in dairy cows." (PMID 38501812, 2024). "Adiponectin is associated with insulin secretion and energy expenditure and is negatively correlated with metabolic disease parameters such as body mass index (BMI), as well as glucose, insulin, triglyceride, and visceral fat levels." (PMID 38672227, 2024). "Interleukin-6 (IL6) is a pleiotropic cytokine implicated in metabolic disorders and inflammation, yet its precise influence on insulin secretion and glucose metabolism remains uncertain." (PMID 38667300, 2024). "Health outcomes associated with metabolic disorders differ among mammalian species and present inherent difficulties to study treatments to improve insulin sensitivity." (PMID 38886475, 2024). "T2DM is a metabolic disease characterized by chronic hyperglycemia caused by various degrees of inadequate β-cell insulin secretion and/or insulin resistance." (PMID 38307981, 2024). "Deficiency or imbalance in insulin production can lead to metabolic disorders and other health issues." (PMID 38357499, 2024). "Older adults, in particular, experience a decline in hepatic insulin sensitivity and associated metabolic disorders, making them more prone to severe fatty liver." (PMID 39839645, 2024). "It is well known that diet-induced mouse islet hyperplasia is often linked to the persistent elevation of insulin levels, a risk factor for T2D and metabolic disorders." (PMID 38916734, 2024). "Dysfunctional mitochondria have been linked to reduced glucose uptake, impaired insulin signaling, and altered lipid metabolism, which all contribute to the pathophysiology of metabolic diseases." (PMID 39606283, 2024). "DM, a metabolic disorder marked by chronic hyperglycemia, stems from either a deficiency in insulin production or the body’s inability to use insulin effectively." (PMID 39727879, 2024). "These metal ions are essential for insulin production, secretion, and activity, with disruptions in their balance linked to metabolic disorders, including diabetes." (PMID 39926598, 2024). "Several studies give attention to altered interactions of vasopressin and insulin in metabolic diseases and inflammatory processes associated with oxidative stress; however, the knowledge in this field is not yet sufficient." (PMID 39769071, 2024). "Conversely, increased EE due to physical activity improves insulin sensitivity and decreases risk factors for metabolic diseases." (PMID 38354854, 2024).